DANT2 (DXZ4 associated non-coding transcript 2, distal)
Gene: Long non-coding RNA gene on chromosome X (115,694,493 to 115,969,214, reverse strand). Ensembl gene ENSG00000235244.
Diseases named in the same sentence as DANT2 in open-access papers:
DANT2 is named in the same sentence as 1 disease in open-access papers, as found by Europe PMC text mining. Sharing a sentence is not in itself a finding about the gene and the disease.
DANT2 shares sentences with these, for which no sentence is quoted: cervical cancer (1 paper).